APOE (apolipoprotein E)
Diseases named in the same sentence as APOE in open-access papers (continued):
Sharing a sentence is not in itself a finding about the gene and the disease.
atherosclerosis (continued). "In high-fat diet-fed ApoE−/− mice, Romidepsin-enhanced STAT3 acetylation epigenetically modulates VCAM-1 expression to suppress atherosclerosis." (PMID 38031118, 2023). "In this study, we identified upregulated DCLK1 in macrophages in atherosclerotic lesions of ApoE−/− mice fed an HFD and determined that macrophage‐specific DCLK1 deletion attenuates atherosclerosis by reducing inflammation in mice." (PMID 36896602, 2023). "Valsartan can reduce the systolic pressure of Ang II treated ApoE-/- mice, promote the differentiation of CD4+T cells into Th2 cells and Tregs, improve the immune balance, and stabilize the atherosclerosis plaque." (PMID 36911741, 2023). "In the present study, our data suggest that ANGPTL8 knockout attenuated atherosclerosis, we further verified the direct role of ANGPTL8 in atherosclerotic plaque progression of ApoE−/−ANGPTL8−/− mice." (PMID 37294581, 2023). "The atherosclerotic apolipoprotein E knockout (ApoE−/−) mice showed significantly increased intestinal permeability due to the disruption of intestinal tight junction proteins, suggesting that intestinal barrier function might also be crucial in the development of atherosclerosis." (PMID 38041095, 2023). "In an ApoE-/- mouse model, HCW9302 treatment curtailed the progression of atherosclerosis through Treg activation and expansion, M2 macrophage polarization and myeloid-derived suppressor cell induction." (PMID 36761778, 2023). "In comparison to ApoE−/−;MC4R+/+ mice, ApoE−/−;MC4RTB/TB mice exhibited exaggerated atherosclerosis." (PMID 37957201, 2023). "In the current study, we used female WTD-fed APOE*3-Leiden mice, since they develop NASH and liver fibrosis concomitantly with atherosclerosis and respond well to statins." (PMID 37175538, 2023). "Based on the anti-atherosclerotic function of S1P demonstrated in vitro and in vivo, the effects of treatment with FTY720 on the development of atherosclerosis were examined in vivo in LDL-R−/− and ApoE−/− mice." (PMID 36671005, 2023). "The use of ApoE −/− mice to study the connection between TMAO and atherosclerosis was mentioned in the previous section on vascular diseases." (PMID 36830968, 2023). "Photomicrographs of the aorta of the ApoE and AIP1 knockout mice showed a greater area of atherosclerosis plague development compared to ApoE knockout mice." (PMID 38024366, 2023). "In the ApoE(−/−) mice study, we demonstrated the alleviation effect of metformin in exacerbation of IAV-induced atherosclerosis." (PMID 37810823, 2023). "Other data, obtained from ApoE-/- mice, suggest that exendin-4 could have beneficial effects against atherosclerosis without affecting metabolism and could potentially prevent the progression of atherosclerosis by its direct action on cells involved in atherosclerosis." (PMID 37401947, 2023). "In ApoE−/− mice studies, blocking CXCL-10 was shown to inhibit the formation of atherosclerosis and resulted in the development of a more stable plaque phenotype." (PMID 37569355, 2023). "Lesion area in aortic roots was also analyzed: atherosclerotic lesion area in the roots of apoE−/− mice was 100,405 ± 27,024 μm2, and CETP expression significantly increased atherosclerosis in apoE−/− mice (416,848 ± 80,959 μm2)." (PMID 37004910, 2023).
atherosclerosis (continued). "The efficacy of statins in reducing atherosclerosis has been extensively described in the literature and has been confirmed in the WTD-fed APOE*3-Leiden mouse model." (PMID 37175538, 2023). "This suggests that RS administration has anti-inflammatory effects in the early stages of atherosclerosis and that RS significantly suppresses macrophage accumulation and proliferation in the inflammatory lesions of the aorta of HFD-fed ApoE−/− mice." (PMID 37998401, 2023). "HDAC3 protects against atherosclerosis through inhibition of inflammation via the microRNA-19b/PPARγ/NF-κB axis in ox-LDL treated HUVECs and ApoE−/− mice." (PMID 38031118, 2023). "To examine the mechanism of SRC-3-mediated promotion of atherosclerosis, we performed messenger RNA (mRNA) sequencing in the aortas of WD-fed SRC-3-/-ApoE-/- and SRC-3+/+ApoE-/- mice." (PMID 36263184, 2022). "In apoE mice fed with HFD, atherosclerosis and blood lipid levels have recently been shown to be alleviated by HDAC11-AS1." (PMID 36339432, 2022). "However, 6 years later, the success of apolipoprotein E (ApoE)-knockout pigs reproduced the human-like atherosclerotic lesions induced by a high-fat, high-cholesterol diet when the model had severe hypercholesterolemia, making a better representation of atherosclerosis in transgenic pig models." (PMID 36325365, 2022). "To determine mechanism of atherosclerosis in SLE, we crossed ApoE−/− mice with Fas−/− mice and generated double-mutant ApoE−/−Fas−/− mice." (PMID 35850768, 2022). "In HFD-induced atherosclerosis in ApoE-/- mice, BBR significantly reduced atherosclerosis in mice and increased the level of Akkermansia." (PMID 36105164, 2022). "In accordance with these findings, we observed that miR-155-5p expression significantly increased in aortic roots from ApoE−/− fed with HFD, a model of advanced atherosclerosis, as well as in carotid biopsies from patients with advanced atherosclerosis." (PMID 36142173, 2022). "Apolipoprotein E (apoE) exists as a part of chylomicron remnants VLDL, IDL and HDL, which has the ability to protect against atherosclerosis by promoting lipid clearance." (PMID 36551995, 2022). "We compared atherosclerosis lesion extent and severity, lesion lipid and macrophage cell content, and plasma lipids in BCG vaccinated and control (saline-treated) adult ApoE−/− mice (16 weeks of age)." (PMID 36290415, 2022). "In this study, we showed that the genetic ablation of SRC-3 prevented the development of atherosclerosis in ApoE-/- mice, indicating that SRC-3 injures the vasculature during atherosclerosis." (PMID 36263184, 2022). "In this report, we performed 1H-NMR based metabonomics research to explore the metabolic changes in ApoE−/−;SAP−/− mice during atherosclerosis progression and clarify the metabolic regulation of SAP deletion in atherosclerosis inhibition." (PMID 36557316, 2022). "In ApoE−/− STZ-induced-DM mice, ALA (1.65 g/kg od) reduced plasma lipid peroxidation, and increased erythrocyte GSH, and PON activity, slowing atherosclerosis." (PMID 35883899, 2022). "To determine the effect of αIL17A Affibody molecule in development of atherosclerosis in vivo, we administered αIL17A Affibody molecule or PBS as sham interperitoneally in ApoE−/− mice." (PMID 35282365, 2022).
atherosclerosis (continued). "In ApoE−/− mice, resveratrol (10 mg/kg od) for 6 weeks decreased macrophage differentiation, increased monocytes GSH and decreased atherosclerosis." (PMID 35883899, 2022). "We investigated the role of NF-κB signalling in SMCs in atherosclerosis by employing SMC-specific ablation of NEMO, an IKK complex subunit that is essential for canonical NF-κB activation, in ApoE−/− mice." (PMID 35869246, 2022). "Thus, we next decided to retest the Nox5 hypothesis of atherosclerosis under conditions where atherosclerosis is observed and determine whether Nox5 KI aggravates this phenotype in the atherosclerosis prone apolipoprotein E (ApoE−/−) mouse in both normal and diabetic conditions." (PMID 35798762, 2022). "Consistently in early aortic atherosclerotic lesions of ApoE−/− mice, mtDNA integrity is decreased, O2•− is increased, and treatment with a mitochondrion-targeted antioxidant significantly reduces H2O2 and atherosclerosis." (PMID 35883899, 2022). "In conclusion, in a murine model of atherosclerosis, vaccination with a single subcutaneous dose of BCG soon after birth reduced the severity of atherosclerosis in 16-week-old adult ApoE−/− mice compared to control mice." (PMID 36290415, 2022). "Our results showed that the ApoE−/− Fas−/− mice simultaneously exhibited SLE and atherosclerosis characteristics." (PMID 35850768, 2022). "We established ApoE and NOS3 double knockout mice with typical clinical features of hypertension and atherosclerosis." (PMID 36360235, 2022). "To verify the effect of ox‐LDL‐M‐EVs miR‐19b‐3p on atherosclerosis and VSMCs in mice, we injected PKH26 (red fluorescent)‐labelled M‐EVs into ApoE−/− mice." (PMID 34910364, 2022). "Therefore, we believe that although SAP deficiency can improve the disorder of acetate in ApoE−/− mice, it cannot change the disorder of TCA circulation in atherosclerosis only by regulating acetate, which may be related to the negative feedback regulation of the body itself." (PMID 36557316, 2022). "HFD-fed ApoE−/− mice irradiated and reconstituted with MPO−/− bone marrow show reduced atherosclerosis; MPO−/− mice and wild-type WT mice treated with an MPO inhibitor show reduced neointima formation following ischemia reperfusion (I/R) injury." (PMID 35883899, 2022). "In ApoE−/− mice, transgenic overexpression of human GPX4 delays the development of atherosclerosis by reducing lipid peroxidation." (PMID 36192693, 2022). "In this study, ApoE−/− mice were given a tail-vein injection of BAG3-overexpressing lentivirus and fed a 12-week high-fat diet (HFD) to investigate the role of BAG3 in atherosclerosis." (PMID 35893075, 2022). "ApoE−/− and Fas−/− mice on the B6 background were cross-bred to generate SLE mice with atherosclerosis." (PMID 35850768, 2022). "Herein, we report the effects of P210-PAM immunization on immune responses in atherosclerosis and tested the translational application of the P210-PAM formulation as a potential human vaccine using A2Kb-Tg ApoE–/– mice." (PMID 35536648, 2022). "To explore the significance of these findings for atherosclerosis, we performed a new series of experiments to compare atherosclerotic lesion development in ApoE−/−/S1PR3−/− mice versus ApoE−/−/S1PR3+/+ mice on a Western diet for 12 weeks with and without DOP." (PMID 36077004, 2022).
atherosclerosis (continued). "The knockdown of RNCR3 in mice models (ApoE–/– and C57BL/6J) results in aggravated hypercholesterolemia and excessive release of inflammatory factors that enhance atherosclerosis development." (PMID 36082127, 2022). "APOE mice heterozygous for ATM display accelerated metabolic syndrome and atherosclerosis, indicating that genetic suppression of the ATM-AMPK pathway contributes to the development of dysfunction." (PMID 35196199, 2022). "In conclusion, ApoE/NOS3−/− adult mice are a satisfactory model of hypertension and atherosclerosis and can be utilized for studies on cardiovascular diseases." (PMID 36360235, 2022). "In agreement with our previous study on the role of PSRC1 in atherosclerosis, double-knockout of PSRC1 and apoE significantly accelerated plaque formation compared with apoE knockout mice, reconfirming the atherosclerosis-protective effect of PSRC1." (PMID 35613310, 2022). "We also show that TET1s can significantly delay the development of atherosclerosis by comparing two different knockout mice, ApoE-/-TET1-/- and ApoE-/-TET1cs/cs." (PMID 35342333, 2022). "To assess the role of CLEC4A2 in hyperlipidemic conditions, we generated ApoE−/− and ApoE−/−Clec4a2−/− littermate mice and fed them a chow diet or a HFD for 12 weeks to allow for the development of atherosclerosis." (PMID 35017526, 2022). "Moreover, high-fat diet feeding in TCTP-TG also did not cause atherosclerosis and the animals exhibited normal lipid metabolism, suggesting that ApoE genetic malfunction may be a prerequisite for establishing atherosclerosis." (PMID 36359240, 2022). "In this study, ApoE-/- mice fed with an HFD developed distinct atherosclerotic lesions in the aorta suggesting that it is a good and reproducible model for studying atherosclerosis." (PMID 36286043, 2022). "Deletion of OPG in apolipoprotein E knockout mice accelerated calcified atherosclerosis, suggesting that OPG can prevent such process of atherosclerosis." (PMID 35523775, 2022). "Flavanone naringenin improved atherosclerosis, increased HDL and Gpx-3 levels, and promoted cell autophagy in high-fat-diet (HFD)-fed apoE−/− mice." (PMID 36297390, 2022). "Treating ApoE−/− mice with tertbutyl hydroquinone (TBHQ), an NRF2 inducer, had a protective effect on atherosclerosis." (PMID 35480874, 2022). "However, germline deletion of AnxA2 did not reduce atherosclerosis burden in ApoE-deficient mice." (PMID 36313572, 2022). "In this study, we revealed its roles in atherosclerosis development using oxidative low-density lipoprotein (ox-LDL)-induced endothelial dysfunction models and a Western diet-induced ApoE−/− mouse model." (PMID 35455042, 2022). "The group then extended these studies to an atherosclerosis mouse model, where elimination of GPNMB-positive cells in an Apolipoprotein E KO mouse (ApoE KO) model also decreased the aortic plaque area." (PMID 36819765, 2022). "In CD40−/− ApoE−/− mice that lack CD40 as well as the ApoE receptor, thus suffering from a severely impaired capability to handle cholesterol, reduced atherosclerosis progression was observed in comparison to control mice when subjected to a high-fat diet." (PMID 36267276, 2022).
atherosclerosis (continued). "On the other hand, too high LCAT overload gives rise to very large HDLs rich in CEs (apoE-rich HDL1), dysfunctional in CE delivery to the liver, which can lead to increased atherosclerosis." (PMID 36297390, 2022). "In another mouse model of atherosclerosis, SCN− supplementation also reduced plaque size in apolipoprotein E−/− mice and reduced oxidative damage while improving endothelial function." (PMID 36552550, 2022). "To further elucidate the role of Grp94 in atherosclerosis, we examined the effect of HCP1 on the atherosclerotic plaque in apoE−/− mice." (PMID 34938782, 2021). "For atherosclerosis and CVD, treatment with BMS309403 significantly reduced the atherosclerotic lesion area in the proximal aorta in diabetic ApoE-/- mouse models." (PMID 34502295, 2021). "Therefore, we constructed models with macrophages treated with ox-LDL and ApoE-/- mice fed with high-fat diet to explore the specific regulatory mechanism of EVs-containing miR-503-5p from macrophages as a mean to communicate with ECs and SMCs in the biology of atherosclerosis." (PMID 33872218, 2021). "Lentivirus-mediated hepatic expression of hEp in apoE-null mice reduced plasma VLDL and LDL-C concentrations and also decreased atherosclerosis." (PMID 33800446, 2021). "The role of GPR55 in monocyte adhesion and atherosclerosis development was investigated in human THP-1 monocytes and ApoE−/− mice using O-1602 (a potent agonist of GPR55) and CID16020046 (a specific GPR55 antagonist)." (PMID 34884889, 2021). "Deletion of RAGE attenuates leukocyte recruitment and protects against atherosclerosis by reducing oxidative stress and decreasing the expression of proinflammatory markers, including NF-κB p65, VCAM-1, and MCP-1, in diabetic ApoE(–/–) mice." (PMID 33937238, 2021). "In ApoE−/− mice, the specific overexpression of LOX-1 in the endothelium promotes atherosclerosis and inflammation." (PMID 34066436, 2021). "In our previous studies, administration of mangiferin, a xanthonoid extracted from Salacia oblonga, is protective against atherosclerosis by elevating plasma HDL-C levels and promoting RCT in apoE−/− mice." (PMID 33692340, 2021). "Here, we synthesize clinical data on cholesterol, atherosclerosis, APOE, and VCID into a working model; we posit that atherosclerosis and APOE4 promote reoccurring occlusion and ischemia that eventually lead to VCID." (PMID 33841127, 2021). "ApoE-knockout (ApoE−/−) mice are characterized by high remnant lipoprotein and low HDL levels and consequently develop spontaneous hyperlipidemia and atherosclerosis, making themselves widely used to evaluate the impact of therapeutic agents on atherogenesis." (PMID 34564147, 2021). "Furthermore, a recent study suggested that miR-34a may be a promising target for the treatment of atherosclerosis as prevents cell growth and promotes apoptosis in atherosclerosis by regulating Bcl2, while deletion of miR-34a ameliorates atherosclerotic lesions in high-fat diet induced ApoE−/− mice." (PMID 35155600, 2021). "In this study, we induced atherosclerosis in apoE–/– mice by feeding them with a high-fat diet (HFD) and observed the therapeutic efficacy of rSj-Cys in reducing atherosclerosis and atherosclerotic renal damage." (PMID 34901005, 2021). "We constructed ApoE‐/‐LXN‐/‐ double knockout mice, and the atherosclerosis model was established by feed the mice with high‐fat diet for 16 weeks." (PMID 34085389, 2021).